SH3BGRL3 (SH3 domain binding glutamate rich protein like 3)
Description:
Could act as a modulator of glutaredoxin biological activity (Probable). May play a role in cytoskeleton organization.
Synonyms: SH3BP-1; TIP-B1; HEL-S-297
Tractability: Antibody: its Gene Ontology location is reachable by antibodies, with medium confidence. PROTAC: ubiquitination databases record sites on it; its protein half-life has been measured.
Gene: Protein-coding gene on chromosome 1 (26,280,057 to 26,281,522, forward strand). Ensembl gene ENSG00000142669.
Subcellular location: Cytoplasm, cytosol; Cell projection, ruffle membrane; Nucleus
Subcellular location (Human Protein Atlas): Nuclear bodies
Gene Ontology:
Molecular function: glutathione transferase activity; protein binding
Biological process: cytoskeleton organization
Cellular component: cytosol; extracellular exosome; nucleus; ruffle membrane
Genetic constraint (gnomAD): Loss-of-function variants: 8 observed, 11.89 expected, observed/expected ratio (o/e) 0.67, 90% interval 0.39 to 1.21. The upper end of that interval is the gene's LOEUF score, 1.21, which puts it in group 5 of 6, group 1 being the genes least tolerant of losing a copy. Missense variants: 119 observed, 117.56 expected, observed/expected ratio (o/e) 1.01, 90% interval 0.87 to 1.18. Synonymous variants: 55 observed, 52.3 expected, observed/expected ratio (o/e) 1.05, 90% interval 0.85 to 1.32.
Homologues: Orthologues: dog SH3BGRL3 (100% identical), rabbit SH3BGRL3 (100% identical), pig SH3BGRL3 (98% identical), rat Sh3bgrl3 (98% identical), chimpanzee SH3BGRL3 (97% identical), mouse Sh3bgrl3 (96% identical), guinea pig SH3BGRL3 (95% identical), tropical clawed frog sh3bgrl3 (57% identical), zebrafish sh3bgrl3 (57% identical). Paralogues in human: SH3BGRL2 (43% identical), SH3BGR (41% identical), SH3BGRL (41% identical).
Diseases named in the same sentence as SH3BGRL3 in open-access papers:
SH3BGRL3 is named in the same sentence as 31 diseases in open-access papers, as found by Europe PMC text mining. Sharing a sentence is not in itself a finding about the gene and the disease. The quoted sentences say what the papers report.
bladder cancer (3 papers, 2017 to 2020). "SH3 domain-binding glutamic acid-rich protein-like 3 (SH3BGRL3), a thioredoxin superfamily member, shows a significant association with increased levels of EGFR in bladder cancer." (PMID 32922662, 2020). "SH3BGRL3 was upregulated in glioblastoma multiformand primary bladder cancers as compared to non-tumor tissues, and was detected inurothelial carcinoma patient urine." (PMID 28404947, 2017).
glioblastoma (3 papers, 2019 to 2024). The most malignant astrocytic tumor (WHO grade IV). "High Sh3bgrl3 expression is found in glioblastoma and associated with worse survival in affected patients." (PMID 39178313, 2024).
kidney clear cell carcinoma (3 papers, 2019 to 2023). "Also, a correlation was found between high expression of SH3BGRL3 and tumor progression in kidney clear cell carcinoma (KIRC); moreover, SH3BGRL3 knockdown inhibited KIRC cells proliferation, migration and invasion in vitro, and suppressed tumor growth and metastasis in vivo." (PMID 34380438, 2021).
urothelial carcinoma (3 papers, 2019 to 2021). A malignant neoplasm derived from the transitional epithelium of the urinary tract (urinary bladder, ureter, urethra, or renal pelvis). "Recently it was shown in urothelial carcinoma cells that SH3BGRL3 can only indirectly interact with EGFR following stimulation of the cells with EGF for 10–30 min and that this interaction occurs through Grb2." (PMID 34380438, 2021). "SH3BGRL3 promotes EMT, cell migration, and proliferation of urothelial carcinoma in vitro." (PMID 32922662, 2020).
breast carcinoma (2 papers, 2019 to 2021). "The ErbB2-positive breast cancer cell line SKBR3, a widely used model to study ErbB2 expression, was chosen to assess the co-localization of SH3BGRL3 and ErbB2 proteins by confocal microscopy." (PMID 34380438, 2021). "High expression of CSNK2B (p = 0.0041, HR = 1.37), GRPEL1 (p = 0.0200, HR = 1.29) and QARS (p = 0.0350, HR = 1.26) were corelated with worse prognosis in breast cancer patients, whereas CCND3, HDAC3, SH3BGRL3, SRM, and UBE2D4 were not correlated with OS." (PMID 31781497, 2019).
ischemic stroke (2 papers, 2025 to 2026). A stroke disorder caused by obstruction of blood flow to the brain, due to thrombotic (local blood clot formation) or embolic (due to a blood clot or other material traveling from another site) event. "In conclusion, we found causal evidence supporting three classic genes MMP12, F11 and SCARA5, and three novel genes SH3BGRL3, SWAP70 and SPATA20 were associated with the risk of ischemic stroke and their subtypes." (PMID 41488603, 2026). "There were 8 proteins shared between epilepsy and ischemic stroke: SH3BGRL3, BPNT1, PTPMT1, PACSIN3, MIPEP, CMC2, ABCA5, and PTK2B." (PMID 40624693, 2025).
Stroke (2 papers, 2025 to 2026). Sudden impairment of blood flow to a part of the brain due to occlusion or rupture of an artery to the brain. "We identified 7 potential risk genes (MMP12, F11, SH3BGRL3, ENGASE, SCARA5, SWAP70 and SPATA20) of stroke with altered protein abundances in the plasma." (PMID 41488603, 2026). "This analysis was restricted to four genes, F11, SWAP70, SH3BGRL3 and SPATA20, which showed evidence of an effect in both MRs with risk factors and stroke outcomes." (PMID 41488603, 2026). "The PWAS identified 7 genes (MMP12, F11, ENGASE, SH3BGRL3, SPATA20, SWAP70, SCARA5) whose cis-regulated plasma protein levels were associated with stroke and its subtypes at a FDR of P < 0.05." (PMID 41488603, 2026). "We found that the protein abundance of seven genes (MMP12, F11, SH3BGRL3, ENGASE, SCARA5, SWAP70 and SPATA20) in the plasma was associated with stroke and its subtypes, and six genes (MMP12, F11, SH3BGRL3, SCARA5, SWAP70 and SPATA20) causally related with stroke and its subtypes." (PMID 41488603, 2026). "Notably, we found eight proteins shared by stroke and epilepsy (e.g., SH3BGRL3, PTPMT1), nine shared by epilepsy and VaD (e.g., DOCK7, BCAN), and ten by stroke and VaD (e.g., MTHFR, UVRAG), suggesting common pathogenic axes like inflammation and cellular stress." (PMID 40624693, 2025).
adenoma (1 paper, 2022). A neoplasm arising from the epithelium. "Specific paired miRNA/mRNA networks, including hsa-miR-34a-5p/SLC12A2, hsa-miR-15b-5p/SLC12A2, hsa-miR-195-5p/SLC12A2, hsa-miRNA-502-3p/OLFM4, hsa-miRNA-6807-5p/ZG16, and hsa-miRNA 3064-5p/SH3BGRL3, were identified in samples of adenoma, IMC, and CRC with the MSS phenotype." (PMID 35875068, 2022).
atrial fibrillation (1 paper, 2026). A disorder characterized by an electrocardiographic finding of a supraventricular arrhythmia characterized by the replacement of consistent P waves by rapid oscillations or fibrillatory waves that vary in size, shape and timing and are accompanied by an irregular ventricular response. "The effect of F11, SH3BGRL3, SPATA20 and SWAP70 on each subtype was mediated by Factor XI inhibitors, atrial fibrillation, type 2 diabetes and systolic blood pressure, respectively (P < 0.05)." (PMID 41488603, 2026).
leukemia (1 paper, 2023). A malignant (clonal) hematologic disorder, involving hematopoietic stem cells and characterized by the presence of primitive or atypical myeloid or lymphoid cells in the bone marrow and the blood. "Therefore, by exploring the effect of SH3BGRL3 on the malignant proliferation of leukemia, we further studied the role of circRNA produced by its exon cyclization in the occurrence and development of tumors." (PMID 37397256, 2023).
cancer (10 papers, 2016 to 2025). A tumor composed of atypical neoplastic, often pleomorphic cells that invade other tissues. "SH3BGRL3 is associated with the malignant proliferation of tumors and is involved in tumor progression in many different types of cancer." (PMID 37397256, 2023). "SH3 domain-binding glutamic acid-rich-like protein 3 (Sh3bgrl3) protein is implicated in cell redox homeostasis and is known to be upregulated in some cancers, and potentially involved in cell resistance to TNF-α induced apoptosis." (PMID 32973493, 2020). "SH3BGRL3 appears to promote cancer cell proliferation, epithelial-mesenchymal transition (EMT), and cell migration." (PMID 28404947, 2017). "Another enriched cancer-related pathway is VEGFA-VEGFR2 Signaling Pathway which was enriched by RAP1A, SH3BGRL3, and ITGB1." (PMID 35176998, 2022). "Conversely, over-expression of SH3BGRL3 was found to enhance the migration capacity of MDA-MB-231 cells, as also observed in other cells, such as urothelial and kidney carcinoma cells." (PMID 34380438, 2021). "Another protein of interesting function is SH3BGRL3, which causes resistance to apoptosis induced by TNF in normal and cancer cells." (PMID 27050469, 2016).
tumor (6 papers, 2012 to 2025). "Immunohistochemistry results in 20 surgically resected LACs and adjacent normal tissues showed that IGKC, AAT and SH3BGRL3 were more highly expressed in tumor cells as compared to non-tumor tissues." (PMID 28404947, 2017). "We found a large down-regulation of SH3BGRL2 mRNA levels and even though the other two family members, SH3BGRL and SH3BGRL3, were not significantly down-regulated both showed lower expression in tumours (−1.7 and −3.2 fold respectively) indicating that the whole family may be decreased in tumours." (PMID 22530001, 2012).
neurological disorders (1 paper, 2022). "Of these, SH3BGRL3 has already been linked to SCZ and PSEN1, B9D2, and CXCR5 as well as DNAJB2 and were implicated in other neurological disorders." (PMID 36344995, 2022).
SH3BGRL3 also shares sentences with these, for which no sentence is quoted: acute myeloid leukemia (1 paper); autoimmune disease (1); cognitive decline (1); colorectal (1); colorectal cancer (1); diabetic kidney disease (1); epilepsy (1); esophageal carcinoma (1); head-neck carcinoma (1); infection (1); liver carcinoma (1); lung adenocarcinoma (1); nephrotic syndrome (1); neuropathic pain (1); pancreatic ductal adenocarcinoma (1); papillary thyroid carcinoma (1); rectum adenocarcinoma (1); type 2 diabetes (1).